MALAT1 (metastasis associated lung adenocarcinoma transcript 1)
Diseases named in the same sentence as MALAT1 in open-access papers (continued):
Sharing a sentence is not in itself a finding about the gene and the disease.
tumor (continued). "Since, MALAT1 is oncogenic in our model, we expected the miRNAs sponged by it to be tumor suppressive and that was the case as all sponged miRNAs, including the most affected miRNA, miR-124, are all tumor suppressive miRNAs." (PMID 36059695, 2022). "Two long non-coding RNAs (lncRNAs) (MALAT1, NEAT1) were upregulated in both tumor cells and tumor-associated fibroblasts compared to matched normal mesenchymal cells, suggesting remodeling of fibroblasts by AML cells." (PMID 36028490, 2022). "MALAT1 was also found to be upregulated in gastrointestinal cancer tissues and its higher expression correlated with larger tumor size and lymph node metastasis." (PMID 35682549, 2022). "This condition contributes to the oncogenic role of MALAT1 in tumor cell proliferation and invasion." (PMID 35740569, 2022). "Depleting JMJD2C or MALAT1, or restoring miR-503-5p exerted anti-tumor effects on NSCLC cells in vitro and in vivo." (PMID 35046387, 2022). "MALAT1 has been considered as the prognostic cytokine that initially marked to be the survival marker, due to that it is related to tumor migration, metastasis, and recurrence among NSCLC patients." (PMID 35609308, 2022). "MALAT-1 is expressed exclusively in cervical carcinoma cell lineages and tumor tissues contaminated with HR-HPV." (PMID 35886037, 2022). "While several studies have suggested that MALAT1 has a pro-growth effect on tumor cells and that MALAT1 depleted cells undergo G1/S cell cycle arrest, recent studies postulate a tumor suppressive role of MALAT1." (PMID 36077530, 2022). "Since MALAT1 did not have covariance with significant prognostic factors including size of tumor, number of tumors, tumor stage, and gender, we constructed prediction models for progression rate and survival rate based on MALAT1 and those factors." (PMID 36685103, 2022). "In the initial cohort, we analysed the MALAT1 expression levels in a series of 164 tumour tissues from primary CRC patients with known clinical/pathological status and long-period follow-up outcomes." (PMID 35558512, 2022). "In a multivariate Cox regression model for MALAT1 expression and baseline clinical information (age, gender, tumor stage, and tumor grade), MALAT1 independently predicted shorter PFS (p = 0.023)." (PMID 36685103, 2022). "Univariate analysis showed that sex, HBsAg, tumor number, tumor diameter, TNM stage, and MALAT1 expression were significantly associated with OS and PFS." (PMID 36685103, 2022). "Most of these studies reported that CRC patients with higher MALAT1 expression in tumour tissues had worse clinical outcomes with a shorter OS or DFS." (PMID 35558512, 2022). "Taken together, these findings emphasize the MALAT1-hsa-miR-212-3p network as a master upstream regulator targeting downstream Hh pathway-associated genes in LUAD and UCEC tumor samples." (PMID 36084949, 2022). "For example, MALAT1 can promote tumor metastasis chiefly by regulating epithelial-to-mesenchymal transition in NSCLC." (PMID 35311148, 2022). "In HCC, the MALAT1-miR195-EGFR and MALAT1 miRNA-204-SIRT1 ceRNA networks have previously been linked to tumor cell migration and invasion." (PMID 36217480, 2022). "In a preclinical study, matastasis associated lung adenocarcinoma transcript 1 (Malat1)-specific ASO along with nucleus-targeting peptide gold nanoparticles, reduced Malat1 expression and suppressed metastatic tumor nodule formation in vivo." (PMID 36009578, 2022). "In mice, when MALAT-1 was silenced by siRNA-MALAT-1, the tumor significantly reduced its volume and weight, and the formation of autophagosomes was observed." (PMID 36291856, 2022). "Summarizing, TRAMP tumor cells exhibited primary resistance towards androgen inhibition enhanced through basal cell function and MALAT1 gene fusions." (PMID 35159020, 2022). "Subsequently analyzed by Pearson test, we found the positive correlations between levels of JMJD2C and MALAT1 in tumor tissues." (PMID 35046387, 2022).
tumor (continued). "In BC, lncRNAs are emerging as master regulators of tumour biology, with oncogenic functions associated with tumorigenesis and tumour progression (HOTAIR, MALAT-1, lincRNAp21, and GAS5)." (PMID 35525949, 2022). "One study had indicated that miR-142-3p exerts a tumor suppressor effect in NSCLC by inhibiting the MALAT1/β-catenin signaling pathway." (PMID 35311148, 2022). "The expression of SOX17 and miR-199a was downregulated and that of HIF1α and MALAT1 was upregulated in tumor tissues of mice in the KYSE150R + oe-NC group." (PMID 35614065, 2022). "JMJD2C is mainly located in the nuclei of CRC cell lines and decreases the levels of H3K9me3 and H3K36me3 on the MALAT1 promoter to enhance the transcriptional level of MALAT1, which promotes tumor growth and metastasis in CRC." (PMID 35429301, 2022). "As indicated by the outcome, JMJD2C and MALAT1 were highly expressed in NSCLC tissues compared with para-tumor tissues." (PMID 35046387, 2022). "A study showed that miR-142-3p acted as a tumor inhibitor in NSCLC via inhibition of the MALAT1/b-catenin SP." (PMID 36733364, 2022). "The results showed that tumor tissue samples exhibit a significant up-regulation of MALAT1, PTBP1, and PSF in these databases, thus suggesting pathological relevance." (PMID 36563164, 2022). "Immunohistochemical (IHC) staining showed that the expression levels of Ki67 and YAP1 in xenograft tumor tissues of nude mice injected with sh-MALAT1-transfected cells were markedly downregulated." (PMID 34761116, 2021). "The nude mice were injected with stable MALAT1 knockdown Y79 cells, and the tumor volume was measured every 7 days for 28 days." (PMID 34222668, 2021). "Our results suggested that inhibiting the expression of MALAT1 or SRSF1 significantly slowed tumor formation in addition to reducing the size of the formed tumors (p < 0.05)." (PMID 34001131, 2021). "Concerning the prognostic role, there was a correlation between MALAT1 RNA level and survival of tumor patients." (PMID 34308750, 2021). "During tumorigenesis, MALAT1 upregulation promotes increased proliferation and tumor formation in vivo by promoting ZHX1 expression via a competitive, endogenous mechanism that sponges miR-199a." (PMID 33807183, 2021). "MALAT1 is an oncogenic lncRNA that promotes tumor progression and chemoresistance through various mechanisms, such as miRNA sponging and autophagy induction." (PMID 34425750, 2021). "Serum levels of MALAT1 were also positively associated with WHO grade, tumor size, functional impairment, and overall and recurrence-free survival." (PMID 34322395, 2021). "Recently, studies reported the role of miRNAs as tumor suppressors by inhibiting PD-L1 and long non-coding RNAs (lncRNAs) such as MALAT1 and NEAT1." (PMID 34679437, 2021). "Of these genes, MALAT1 and POU5F1 remained significantly associated to tumor location after multi‐testing correction." (PMID 33356003, 2021). "Surprisingly, it has been observed that MALAT1 can also function as a tumor suppressor in breast and colorectal tumors." (PMID 34204094, 2021). "In this study, we conducted experiments to explicate the functions of MALAT1 in EOC progression in the tumor microenvironment (TME)." (PMID 34638541, 2021). "Further functional studies are required to investigate the regulatory mechanisms of MALAT1 in CAFs and the crosstalk with tumor cells in the TME." (PMID 34638541, 2021). "detected the expression of MALAT1 in tumor tissues and adjacent normal tissues in 36 cases of NSCLC using real-time quantitative PCR (qRT-PCR) and found that the expression of MALAT1 was significantly upregulated in NSCLC tissues." (PMID 34778078, 2021). "Our data indicated that inhibition of MALAT1 expression led to a marked reduction in the rate of tumor formation and the size of the formed tumors." (PMID 34001131, 2021).
tumor (continued). "Taken together, our experimental results indicated that further studies on lncRNAs in tumor cells and CAFs are required to facilitate the identification of non-coding transcripts such as MALAT1 for targeted biomarker applications." (PMID 34638541, 2021). "Especially in NSCLC, the high expression of MALAT1 was significantly correlated with tumor node metastasis (TNM) stage, vascular invasion, pathological differentiation, and recurrence." (PMID 34778078, 2021). "Another lncRNA whose expression correlates with advanced tumor stages and reduced overall survival of HCC patients is MALAT1 (metastasis-associated lung adenocarcinoma transcript 1)." (PMID 34439391, 2021). "On the 16th day after the inoculation, the tumor formation rate of the two groups of cells exhibited a significant difference in relation to tumor volume which was notably reduced after si-MALAT1 treatment (p < 0.05)." (PMID 34001131, 2021). "In recent years, several studies have reported the tumor-related functions of MALAT-1 in several types of tumors." (PMID 34858541, 2021). "The results of in vivo experiments using NSCLC mouse models showed that a low expression of MALAT1, miR-197-3p, or p120-ctn can decrease the tumor volume and weight compared with the control group." (PMID 34778078, 2021). "Studies have shown that MALAT1 is involved in tumor proliferation, metastasis, apoptosis, epigenetic regulation, cell signal transduction, and other processes." (PMID 34356052, 2021). "And MALAT1 knockdown also inhibited cell cycle progression and impaired tumor cell migration and invasion." (PMID 34760707, 2021). "Together, our findings demonstrate how MALAT1 overexpression facilitates an oncogenic function through inhibiting tumor cell apoptosis, combined with increasing tumor cell inflammation, proliferation, and invasion in the EOC tumor microenvironment." (PMID 34638541, 2021). "On the 16th day post inoculation, our results demonstrated that depletion of MALAT1 or SRSF1 further reduced the tumor volume while upregulation of MALAT1 markedly increased the tumor size (p < 0.05)." (PMID 34001131, 2021). "The tumorigenic features developed by MALAT1 expression were evidenced by lower proliferation rate, lower colony formation and decreased tumor growth in in vivo models once GBC cells were treated with siRNAs against MALAT1 (siMALAT1)." (PMID 34575316, 2021). "The other studies also demonstrated the high expression of MALAT1 in NSCLC tissues or cells and the association with tumor size and lymphatic metastasis." (PMID 34308750, 2021). "Complex epigenetic regulatory mechanisms involving the histone acetyltransferase enzyme, MYST4 in EOC demonstrated that signaling connecting MYST4 with MALAT1 affects tumor cell proliferation and metastasis in vitro, revealing MALAT1’s oncogenic traits." (PMID 34638541, 2021). "Initially, we assessed the tumor purity and found that RNA level of MALAT1 was significantly related to the tumor purity in eight types of tumors." (PMID 34308750, 2021). "Malat1, a well-studied lncRNA, was systemically knocked down using ASOs in a mouse mammary carcinoma model, and showed lower tumor burden and significant reduction in metastasis." (PMID 34900986, 2021). "PVT1, MALAT1, miRNA-186 and miRNA-101 levels were correlated with E-cadherin, tumor stage, lymph node and distant metastasis." (PMID 34200314, 2021). "In vivo experiments including subcutaneous tumor formation assay and tail intravenous injection were performed to investigate the effects on tumor growth and metastasis when MALAT1 was downregulated." (PMID 34001866, 2021). "MALAT1 depletion caused considerable reduction of tumor growth in tumor bearing mice, while the ectopic expression of MALAT1 significantly promoted tumor growth." (PMID 33511320, 2021). "Others such as MALAT1, LBX2-AS1, ST7-AS1, and DDX11-AS1 play a role in cell proliferation, migration, and tumor invasion, and some were associated with patient survival (OBI1-AS1)." (PMID 35004666, 2021).
tumor (continued). "Whereas overexpression of CCL21 triggered an increase in tumor size, while under-expressed MALAT1-1 or MALAT1-2 diminished the tumor volume (p < 0.05)." (PMID 34001131, 2021). "LncRNA MALAT1 regulates miR-608, a tumor suppressor that inhibits HOXC4, a homeobox family’s transcription factor, and AKT2, an oncogene kinase, leading to apoptosis." (PMID 34439196, 2021). "LncRNA MALAT1 functioned as a tumor growth regulator increased tumor growth, while miR-124 acted as a negative catalyst, suppressing tumor weight, size, and volume." (PMID 34221014, 2021). "Numerous studies have shown that as a biomarker for tumor diagnosis and prognosis, the abnormal expression of MALAT1 in tumor tissues and/or body fluids is highly indicative." (PMID 34899344, 2021). "This characteristic of having a long half-life makes MALAT1 easy to detect in tumor tissues and body fluids." (PMID 34778078, 2021). "Previous studies already illustrated the vital role of MALAT1 in tumor developments including cell growth and metastasis." (PMID 34308750, 2021). "Consistently, an elevated level of MALAT1 in BC was correlated with an increased tumour size and stage, as well as poor prognosis for patients." (PMID 34884658, 2021). "The findings of the molecular mechanisms of MALAT1 in tumor angiogenesis offer a new viewpoint on OS treatment." (PMID 34692524, 2021). "When MALAT1 was knocked down, the tumor growth was seriously affected, and the tumor volume was much smaller than that of control group." (PMID 34001866, 2021). "MALAT1 as a highly conserved lncRNA, has been found to be overexpressed in several human neoplasms and to promote tumor cell invasion and metastasis." (PMID 34993023, 2021). "Once downregulated, MALAT1 effectively leads to the suppression of tumor cell survival, proliferation, the EMT, and cell migration." (PMID 34638541, 2021). "In the case of the RHO GTPase-related lncRNAs, results showed that the subcutaneous delivery of MALAT1 phosphorothioate-modified ASO successfully suppressed primary tumor differentiation." (PMID 34771549, 2021). "With a length of >8,000 nucleotides, MALAT1 (metastasis-associated lung adenocarcinoma transcript 1), also known as NEAT2 (nuclear enriched abundant transcript 2), is one of the first tumor metastasis-associated and highly conserved lncRNAs to be discovered." (PMID 34257576, 2021). "It has been described that high levels of MALAT1 have correlated with tumor aggressiveness and poor survival of TNBC patients." (PMID 34198989, 2021). "In the negative group (upregulated LOC285194, downregulated HOTAIR and MALAT1), a majority of patients still had a low grade tumor with only one out of five patients reporting advanced stage tumor." (PMID 34307387, 2021). "Subsequently, total RNA and protein of nude mice tumor tissues were extracted, and qPCR and western blot experiments were carried out to measure the level of lncRNA MALAT1 and JAK2 protein." (PMID 34987594, 2021). "In NSCLC patients, metastasis-associated lung adenocarcinoma transcript 1 (MALAT-1) has been shown to be highly expressed in the serum, and that the level of exosomal MALAT-1 correlates with tumor stage and metastasis status." (PMID 33317058, 2020). "The up-regulation of MALAT1 in ESCC tissues can impact the degree of tumor progression and is predictive of postoperative survival." (PMID 33123280, 2020). "The tumor suppressor miR-217 is reported to inhibit MALAT1 through the Ago2-mediated pathway in order to inhibit EMT-related metastasis through upregulating E-cadherin and N-cadherin suppression." (PMID 33123473, 2020). "While exosomes derived from metastatic cells promoted CRC tumor growth and the increased tumor masses were suppressed by targeting exosomal MALAT1." (PMID 32209115, 2020). "It was showed that MALAT1 expression is significantly increased in CC than in normal tissues and is correlated with tumor size, FIGO stage, vascular invasion and lymph node metastasis." (PMID 33371204, 2020).
tumor (continued). "MALAT1 is mainly discovered in nuclear speckles and has been reported to be involved in tumor metastasis." (PMID 32174966, 2020). "MALAT1 not only acted as a potential cancer biomarker but also regulated angiogenesis in diabetic retinopathy, tumor, hindlimb ischemia, and brain vascular endothelium." (PMID 32190702, 2020). "The pivot lncRNA, MALAT1, with the largest degree in both ceRNA networks, regulates the proliferation, invasion, and migration potential of metastatic tumor cells by sponging miR-195 in DLBCL." (PMID 33193722, 2020). "The expression of MALAT1 is positively correlated with the proliferation and metastasis of tumor cells." (PMID 32117734, 2020). "MALAT1 is involved in the regulation of genes related to proliferation, apoptosis, and metastasis of tumor cells." (PMID 31479414, 2020). "Compared to normal tissues, the level of MALAT1 was distinctly increased in 30 paired NSCLC tumor tissues, and the same result was observed in the mRNA and protein abundances of MDM4." (PMID 33146951, 2020). "Overexpression of MALAT1 is positively correlated with tumor progression and metastasis in a large number of tumor types such as breast cancer, colon cancer and osteosarcoma." (PMID 33371204, 2020). "It has been found that MALAT1, another lncRNA, have the sponge adsorption function, which promotes tumor cell proliferation and metastasis through sponging many miRNAs." (PMID 33292652, 2020). "In accordance with the result of MALAT1 expression in NSCLC tumor tissues, the enrichment of MALAT1 was also increased in NSCLC cells (A549 and H460) relative to normal BEAS‐2B cells." (PMID 33146951, 2020). "Inhibition of MALAT1 reduced tumor growth of MM by increasing miR-1271-5p and decreasing SOX13 in vivo, insinuating that MALAT1 contributed to tumorigenesis via the regulatory axis of miR-1271-5p/SOX13." (PMID 31953613, 2020). "Metastasis-associated lung adenocarcinoma transcript 1 (MALAT1), also known as nuclear-enriched abundant transcript 2 (NEAT2), is a highly conserved lncRNA that is typically upregulated in various tumour tissues and disordered neurons." (PMID 32972446, 2020). "On top of that, tumor-derived MALAT-1 is transported in exosomes to HUVEC cells, enhancing angiogenesis by dysregulating proangiogenic genes like VEGF in vivo." (PMID 32992718, 2020). "In the tumor tissues of SC groups, MALAT1 and AFAP1-AS1 showed a significant reduction after being treated with high-dose Vc, while the expression of UCA1, which showed a reduction trend in vitro, was increased in SC tumor tissue after high-dose Vc." (PMID 33293956, 2020). "MALAT1 silencing and miR-146a upregulation inhibited tumor properties of HCC cell lines, indicating their potential as therapeutic targets for HCC." (PMID 32435156, 2020). "Herein, we observed that the gapmerization of MALAT1 reversed metabolism in PCa cells and tumor tissue, fostering the partial recovery of glycolytic metabolism." (PMID 33375130, 2020). "Numerous studies have uncovered aberrant expression of MALAT1 in a group of human tumor tissues, suggesting its significant role in many vital biological behavior including tumor cell proliferation, apoptosis, invasion and metastasis." (PMID 31792655, 2020). "Another highly-expressed lncRNA in thyroid cancer, MALAT1, can activate angiogenesis via increasing fibroblast growth factor 2 (FGF2) expression in tumor-associated macrophages." (PMID 33158279, 2020). "As the results indicated, the level of MALAT1 decreased in a stepwise fashion with the increasing level of miR‐145 in tumour/serum samples genotyped as AA, AG and GG, respectively." (PMID 32720739, 2020). "For example, MALAT1-specific siRNA displayed a significant decrease in tumor growth, metastasis, invasion, and cell cycle arrest." (PMID 32575858, 2020).